REXO5 (RNA exonuclease 5)
Synonyms: NEF-sp
Tractability: No criterion of Open Targets' tractability assessment is met for any kind of drug.
Gene: Protein-coding gene on chromosome 16 (20,806,157 to 20,849,668, forward strand). Ensembl gene ENSG00000005189.
Subcellular location (Human Protein Atlas): Nuclear membrane; Endoplasmic reticulum; Nucleoli
Gene Ontology:
Molecular function: exonuclease activity; nucleic acid binding; RNA binding
Biological process: rRNA 3'-end processing
Cellular component: extracellular exosome; nucleolus
Genetic constraint (gnomAD): Loss-of-function variants: 31 observed, 61.06 expected, observed/expected ratio (o/e) 0.51, 90% interval 0.38 to 0.69. The upper end of that interval is the gene's LOEUF score, 0.69, which puts it in group 2 of 6, group 1 being the genes least tolerant of losing a copy. Missense variants: 594 observed, 727.81 expected, observed/expected ratio (o/e) 0.82, 90% interval 0.76 to 0.87. Synonymous variants: 248 observed, 282.5 expected, observed/expected ratio (o/e) 0.88, 90% interval 0.79 to 0.98.
Homologues: Orthologues: chimpanzee REXO5 (99% identical), macaque REXO5 (96% identical), pig REXO5 (86% identical), dog REXO5 (85% identical), rabbit REXO5 (80% identical), guinea pig REXO5 (74% identical), rat Rexo5 (68% identical), mouse Rexo5 (67% identical), tropical clawed frog rexo5 (43% identical), Drosophila melanogaster CG12877 (13% identical), Caenorhabditis elegans pqe-1 (12% identical), Drosophila melanogaster prage (10% identical). Paralogues in human: REXO1 (13% identical), AEN (9% identical), ISG20L2 (8% identical), REXO4 (8% identical), ISG20 (6% identical).
Diseases named in the same sentence as REXO5 in open-access papers:
REXO5 is named in the same sentence as 1 disease in open-access papers, as found by Europe PMC text mining. Sharing a sentence is not in itself a finding about the gene and the disease.
REXO5 shares sentences with these, for which no sentence is quoted: chronic myeloid leukemia (1 paper).